FOSB (FosB proto-oncogene, AP-1 transcription factor subunit)
Description:
Heterodimerizes with proteins of the JUN family to form an AP-1 transcription factor complex, thereby enhancing their DNA binding activity to gene promoters containing an AP-1 consensus sequence 5'-TGA[GC]TCA-3' and enhancing their transcriptional activity. As part of the AP-1 complex, facilitates enhancer selection together with cell-type-specific transcription factors by collaboratively binding to nucleosomal enhancers and recruiting the SWI/SNF (BAF) chromatin remodeling complex to establish accessible chromatin (By similarity). Together with JUN, plays a role in activation-induced cell death of T cells by binding to the AP-1 promoter site of FASLG/CD95L, and inducing its transcription in response to activation of the TCR/CD3 signaling pathway. Exhibits transactivation activity in vitro (By similarity). Involved in the display of nurturing behavior towards newborns (By similarity). May play a role in neurogenesis in the hippocampus and in learning and memory-related tasks by regulating the expression of various genes involved in neurogenesis, depression and epilepsy (By similarity). Implicated in behavioral responses related to morphine reward and spatial memory (By similarity). [Isoform 11]: Exhibits lower transactivation activity than isoform 1 in vitro (By similarity). The heterodimer with JUN does not display any transcriptional activity, and may thereby act as an transcriptional inhibitor (By similarity). May be involved in the regulation of neurogenesis in the hippocampus (By similarity). May play a role in synaptic modifications in nucleus accumbens medium spiny neurons and thereby play a role in adaptive and pathological reward-dependent learning, including maladaptive responses involved in drug addiction (By similarity). Seems to be more stably expressed with a half-life of ~9.5 hours in cell culture as compared to 1.5 hours half-life of isoform 1 (By similarity).
Synonyms: G0S3; GOSB; GOS3; AP-1; MGC42291; DKFZp686C0818
Tractability: Small molecule: a structure with a bound ligand is known.
Gene: Protein-coding gene on chromosome 19 (45,467,995 to 45,475,179, forward strand). Ensembl gene ENSG00000125740.
Subcellular location: Nucleus
Subcellular location (Human Protein Atlas): Nucleoplasm; Vesicles
Pathways (Reactome):
Signal Transduction: Estrogen-dependent gene expression; NGF-stimulated transcription
Immune System: Regulation of PD-L1(CD274) transcription
Gene Ontology:
Molecular function: protein binding; sequence-specific double-stranded DNA binding; DNA binding; DNA-binding transcription factor activity, RNA polymerase II-specific; RNA polymerase II cis-regulatory region sequence-specific DNA binding; DNA-binding transcription activator activity, RNA polymerase II-specific; DNA-binding transcription factor activity; double-stranded DNA binding; sequence-specific DNA binding
Biological process: negative regulation of transcription by RNA polymerase II; regulation of transcription by RNA polymerase II; behavioral response to cocaine; cellular response to hormone stimulus; female pregnancy; positive regulation of transcription by RNA polymerase II; regulation of DNA-templated transcription; response to amphetamine; response to cAMP; response to cocaine; response to corticosterone; response to ethanol; response to mechanical stimulus; response to morphine; response to nicotine; response to progesterone; response to xenobiotic stimulus; transcription by RNA polymerase II
Cellular component: nucleoplasm; nucleus; chromatin; cytosol
Genetic constraint (gnomAD): Loss-of-function variants: 8 observed, 27.01 expected, observed/expected ratio (o/e) 0.3, 90% interval 0.17 to 0.53. The upper end of that interval is the gene's LOEUF score, 0.53, which puts it in group 2 of 6, group 1 being the genes least tolerant of losing a copy. Missense variants: 374 observed, 442.5 expected, observed/expected ratio (o/e) 0.85, 90% interval 0.78 to 0.92. Synonymous variants: 214 observed, 204.85 expected, observed/expected ratio (o/e) 1.04, 90% interval 0.93 to 1.17.
Homologues: Orthologues: chimpanzee FOSB (100% identical), macaque FOSB (99% identical), guinea pig FOSB (98% identical), pig FOSB (98% identical), dog FOSB (98% identical), mouse Fosb (96% identical), rat Fosb (95% identical), rabbit FOSB (81% identical), zebrafish fosb (59% identical), tropical clawed frog fosb (53% identical), Drosophila melanogaster Atf3 (19% identical). Paralogues in human: FOS (43% identical), FOSL2 (40% identical), FOSL1 (33% identical), JDP2 (17% identical), ATF3 (17% identical), BATF2 (14% identical), BATF (11% identical), BATF3 (11% identical).
Diseases named in the same sentence as FOSB in open-access papers:
FOSB is named in the same sentence as 152 diseases in open-access papers, as found by Europe PMC text mining. Sharing a sentence is not in itself a finding about the gene and the disease. The quoted sentences say what the papers report.
breast carcinoma (30 papers, 2005 to 2024). "In addition, the FOSB gene is associated with RFS in breast cancer patients according to Kaplan–Meier plotter." (PMID 32679794, 2020). "CD99SF engagement by antibodies in breast cancer increased the expression of JunD and FosB AP-1 factors, along with the activation of PI3K-Akt signaling pathway by phosphorylation of Src, Akt, p38 MAPK, ERK and JNK." (PMID 38804310, 2024). "To explore it, we analyzed the differentially expressed genes of RPL31+ subset compared with FOSB+ subset in breast cancer as well as mast cells in normal breast tissues, respectively." (PMID 39104420, 2024). "We obtained ChIP-seq data of the candidate transcription factors FOSB (ENCSR569XNP), ZNF302 (ENCFF037UPH), SP1 (ENCFF072FPF), ELK1 (ENCFF123KER), and FOXF2 (ENCFF008ABX) in a breast cancer cell line MCF-7 from ENCODE." (PMID 37173692, 2023). "Consistent with the molecular heterogeneity of breast cancer, this analysis revealed that high Ca2+-induced expression of early response genes FOS/FOSB as well as genes associated with malignant tumors such as MAGEC2 was cell type specific." (PMID 35355564, 2022). "FOSB is a transcription factor that affects tumor differentiation, proliferation, and metastasis in breast cancer." (PMID 35310908, 2022). "According to Kaplan–Meier plotter, low expression of FOSB, GPR153, and MYH4 is associated with poor RFS in breast cancer patients." (PMID 32679794, 2020). "Analysis of Oncomine datasets revealed that FOSB was significantly downregulated in a variety of breast cancer samples." (PMID 32477007, 2020). "A survival analysis of the clinical breast cancer datasets indicated a strong correlation between higher FOSB expression and better relapse-free survival (RFS) (HR = 0.66, 95% CI 0.43–1.41, P = 0.056) in TNBC." (PMID 32477007, 2020). "In conclusion, we have identified (i) TP4 as a novel cytotoxic peptide possibly suitable for breast cancer therapy, and (ii) FOSB as a biomarker of the response to TP4 and anthracyclines, particularly in TNBC." (PMID 27248170, 2016). "These include EIS in the FOSB gene, resulting in the delta FOSB isoform, consistent with previous reports on its differential AS in breast carcinomas." (PMID 25934563, 2015). "Progression of mammary carcinomas involves downregulation of FosB as well as upregulation and phosphorylation of Fra-1 and Fra-2 in an in vivo system." (PMID 23181129, 2012). "The expression of the Jun proteins c-Jun, JunB and JunD as well as the Fos family members c-Fos, FosB, Fra-1 and Fra-2 in the analysed mammary tumour tissues was described in our prior publication." (PMID 15928662, 2005). "The mast cells in breast cancer were divided into FOSB+ and RPL31+ subsets." (PMID 39104420, 2024). "MECOM and FLI1 activities were decreased, while breast cancer promoted FOSB and RFX2 activities." (PMID 37153595, 2023). "However, patients with breast cancer exhibiting upregulated expression levels of FOS, FOSB, EGR1, and EGR3 were associated with improved prognosis." (PMID 37233869, 2023). "In addition, moderate or strong FOSB expression has been confirmed to be correlated with ER-positive status and PR-positive status in breast cancer tissue and cell lines, which is consistent with our findings." (PMID 33102239, 2020). "Moreover, either FOSB or FOSΔB overexpression triggered cell death in all tested breast cancer cells, and FOSB knockdown attenuated TP4-mediated cytotoxicity." (PMID 30551662, 2018). "Cell proliferation, differentiation, transformation.Dimerizes with Jun family members to form the AP-1 transcription factor complex.Loss of FosB in breast cancer associated with hormone receptor negative status and high grading." (PMID 27769065, 2016). "In addition to FOS, FOSB has also been shown to have a function in progression of various tumour types being down-regulated in poorly differentiated mammary carcinomas." (PMID 24865347, 2014).
breast carcinoma (continued). "It was reported that in breast cancer AP-1 transcription factor components, i.e., JUN, JUNB, FOS, FOSB, in addition to DUSP1, EGR1, NR4A1, IER2 and BTG2, behave as a conserved co-regulated network 14, most of which are transcriptional factors." (PMID 37057290, 2023). "The FOS, FOSB, EGR1, and EGR3 expression levels in healthy breast tissues were higher than in breast cancer tissues." (PMID 37233869, 2023). "In breast cancer, eight winning TFs (ZBTB16, KLF2, KLF4, NR2F1, EGR1, FOSB, EPAS1, and GPRASP1) can form a coregulatory network, and three other winning TFs (MYBL2, FOXM1, and TAL1) can form another coregulatory network." (PMID 36101460, 2022). "The overall survival data showed that the prognosis of breast cancer patients was poorer when two genes (FOS and FOSB) were highly expressed or when four genes (JUN, GADD45B, NR4A1, and BTG2) showed low expression levels." (PMID 34457116, 2021). "Therefore, FOSB and ANXA1 can be considered as the important marker to distinguish normal sample from breast cancer." (PMID 37934154, 2023). "Fra-1 is undetectable in most FosB positive breast cancer cells, but it is expressed in FosB negative cell lines." (PMID 37483616, 2023). "Therefore, we hypothesized that FOS, FOSB, EGR1, and EGR3 mainly function as tumor suppressor genes to inhibit the occurrence and progression of breast cancers." (PMID 37233869, 2023). "Similar to most cell-cycle proteins, the expression of c-Fos, Fra-1, Fra-2 and, to a lesser degree, FosB is absent or weak in normal mammary tissue samples, and the data obtained from Western blots with breast cancer specimens probably reflect their expression in tumour cells." (PMID 15928662, 2005). "Strikingly, ER+ and TNBC subtypes exhibited significantly higher RPL31+ subset than FOSB+ subset, whereas the HER2+ subtype exhibited a higher FOSB+ subset than RPL31+ subset, indicating that the imbalance of these two subsets might influence the prognosis of breast cancer patients." (PMID 39104420, 2024). "The over-expressed CCNE1, CLGN, NEK2, PTTG1 and RAD51, and the under-expressed ADAMTS1, FOS, FOSB, IL6 and ZFP36 in tumor cells are examples of breast cancer genes without differential promoter methylation between normal and tumor samples." (PMID 25706888, 2015).
Dyskinesia (23 papers, 2009 to 2025). A movement disorder which consists of effects including diminished voluntary movements and the presence of involuntary movements. "This study shows that dopaminergic depletion is sufficient to induce a striatal upregulation of the 5-HT4R, and that this increase is potentiated, and concomitant with FosB/ΔFosB, following L-Dopa supplementation causing dyskinesias." (PMID 38339940, 2024). "Elevated levels of ΔFosB are associated with a loss of FosB function, which results in the early development of dyskinesia and unstable firing rate changes during the ON phase in L-DOPA-treated animals." (PMID 34640395, 2021). "Actually, FOSB overexpression was previously associated with L-DOPA-induced dyskinesia in nitric oxide synthase-positive striatal interneurons in hemiparkinsonian mice." (PMID 32545328, 2020). "We then analyzed the expression of ΔFosB, a stable truncated splice variant of FosB that has been associated with L-DOPA induced dyskinesia." (PMID 22880070, 2012). "For example, drug-induced dyskinesia and amyotrophic lateral sclerosis are linked together through FOSB Pathway (BioCarta)." (PMID 19194489, 2009). "ΔFosB, a truncated isoform of transcription factor FosB, is an established hallmark of dyskinesia." (PMID 30555300, 2018). "Finally, post-mortem analysis indicated that this reduction in dyskinesias was associated with changes in cFOS, FosB and ARC mRNA expression levels in the putamen." (PMID 23300984, 2013). "Delayed the onset and reduced the severity of dyskinesia.Attenuated already-established dyskinesia.Reduced AIMs and hyperactivity.Lowered levels of FosB protein and histone pAcH3 in the basal ganglia." (PMID 40573285, 2025). "Recently, COX-2 expression was associated with LID development after 14 days of L-DOPA treatment, correlating with LID severity and FosB/ΔFosB expression, as molecular markers of dyskinesia." (PMID 41154463, 2025). "Of note is the observation of a spatial coincidence between the striatal upregulation of 5-HT4R and the striatal increase in FosB/ΔFosB, a transcriptional factor critically involved in L-Dopa-induced dyskinesia pathophysiology." (PMID 38339940, 2024). "FosB is expressed mainly in D1R-containing neurons and correlates with the severity of the dyskinesia manifestation." (PMID 39766413, 2024). "Initial experiments showing that antisense oligonucleotides against fosB reduced dyskinesia were followed by several studies in which LID was exacerbated or reduced by modulating FosB-dependent transcriptional activity." (PMID 29396608, 2018). "First, we demonstrated that the electrical inhibition of FosB/∆FosB dlBST neurons decreased LID severity in the rat model of L-DOPA-induced dyskinesia." (PMID 28539659, 2017). "Double immunolabeling images of the two molecules exhibited colocalization between FosB-ΔFosB and p-H3 in rats with dyskinesia." (PMID 28337120, 2017). "Additionally, we evaluated the effect of TMS on the dyskinesia global score and its molecular marker, FosB, in the striatum (n = 67)." (PMID 39766413, 2024). "In addition, optogenetic stimulation in the cerebellum regularized the aberrant neuronal discharge in the cerebellar nuclei and the motor cortex, controlling FosB overexpression and attenuating dyskinesias." (PMID 39766413, 2024). "Chronic L-DOPA treatment induces FosB/ΔFosB accumulation in the striatum that may result not only in dyskinesia but also an insensitive response to L-DOPA." (PMID 28337120, 2017). "However, in agreement with most of the literature dealing with dyskinesias, significant changes were observed in FosB and cFOS mRNA levels in the putamen of parkinsonian dyskinetic animals that were corrected after sub-chronic treatment with IRC-082451." (PMID 23300984, 2013).
Dyskinesia (continued). "To assess whether a mechanism of TMS involves the modulation of cellular activation in dyskinesias, we evaluated the expression of FosB and c-Fos in the striatum and in D1R-containing cells in the M1 and the striatum of dyskinetic animals compared with naïve (i.e., intact) rats." (PMID 39766413, 2024). "The attenuation of dyskinetic behavior and striatal FosB expression by TMS could indicate that this intervention disrupted the activation of D1R-containing cells, since D1R blockade abolishes FosB signaling and the reduction in FosB transcriptional activity mitigates the severity of dyskinesias." (PMID 39766413, 2024). "Moreover, TMS treatment attenuated dyskinesias, along with a low stratal FosB expression." (PMID 39766413, 2024). "IEGs such as c-Fos, FosB, and ΔFosB, were shown to be increased in the striatum of LID animals, which was positively correlated with dyskinesia severity in a primate model of PD." (PMID 31929116, 2020). "The intake of this compound induced the reduction of FosB striatal protein overexpression and the phosphoacetylation of histone 3, which are molecular markers of L-DOPA-induced dyskinesias." (PMID 32545328, 2020). "The current study showed that TMS depressed FosB and c-Fos expression in D1R+ cells of the dorsal striatum and motor cortex, suggesting a mechanism by which TMS may directly mitigate dyskinesias." (PMID 39766413, 2024). "Similarly, García-Montes and colleagues found that downregulating mGluR5 in D1 neurons in a mouse model of Parkinson’s disease attenuated dyskinesia by decreasing ERK and FosB expression in the striatum." (PMID 34360592, 2021). "However, COX-2 inhibition did not reduce dyskinesia or COX-2 and FosB/ΔFosB expression, while significantly lowering PGE2 levels and oxidative stress in mouse and primate PD models." (PMID 41154463, 2025).